CAV2 (caveolin 2)
Diseases named in the same sentence as CAV2 in open-access papers (continued):
Sharing a sentence is not in itself a finding about the gene and the disease.
lung carcinoma (11 papers, 2011 to 2024). "Taken together, our data suggest that host deficiency in Cav-2 causes tumor regression in two independent syngeneic models of lung cancer growth in immunocompetent mice involving s.c. injection of LLC and CMT 167 lung carcinoma cells." (PMID 31831780, 2019). "CAV2 overexpression involves in promoting tumor growth, metastasis and angiogenesis in lung cancer and pancreatic cancer." (PMID 38093298, 2023). "Among the significant analyses, 70% of the study revealed that CAV1 and CAV2 were all significantly downregulated in most tumor types, especially in BC, lung cancer, ovarian cancer, prostate cancer, bladder cancer, and sarcoma cancer." (PMID 36147736, 2022). "Remarkably, even a more robust tumor growth inhibitory phenotype was observed in Cav-2 KO mice in the latter model of lung cancer growth compared to LLC model." (PMID 31831780, 2019). "To examine the role of host-expressed Cav-2 in lung cancer progression, we used LLC26 and CMT 16727 as the two independent murine lung carcinoma cell lines derived in C57BL6 background." (PMID 31831780, 2019). "To explore the relationship between stromal CAV1 and CAV2 expression and lung cancer, we analyzed expression for both proteins in stromal cells of the primary tumor as well as lymph nodes of human lung cancer tissues placed on TMAs." (PMID 29850392, 2018). "The aim of this study was to investigate the clinicopathological significance and prognostic value of stromal CAV1 and CAV2 expression in lung cancer." (PMID 29850392, 2018). "A first interesting observation about these genes is that many of them have been positively implicated in breast and/or lung cancer progression and resistance to therapy: AURKA, CAV2, RAB27A, RAD51, TIMELESS, TIMM17A." (PMID 22347440, 2012). "In all types of lung cancer, CAV2 is dysregulated at the RNA and protein levels." (PMID 35178391, 2022). "Here, we demonstrate that host deficiency in caveolin-2, a member of caveolin protein family, increases M1-polarized tumor-associated macrophage (TAM) and CD8 T cell infiltration into subcutaneously implanted murine lung carcinoma tumors." (PMID 31831780, 2019). "The stromal CAV2 expression was evaluable in 150 in primary lung cancer tissues." (PMID 29850392, 2018). "Furthermore Cav1 and Cav2 are down regulated, according to previously published results showing a tumor suppressor activity of Caveolin-1 and its down-regulation during lung cancer development." (PMID 21205295, 2011). "Collectively, our data suggest that lung cancer cells use caveolin-2 expressed in bone marrow-derived cell types including TAMs to promote tumor growth via suppressing the anti-tumor immune response and that caveolin-2 could be a potential target for cancer immunotherapy." (PMID 31831780, 2019). "In detail, according to the different types of lung cancer, CAV1, CAV2, CAVIN1 and CAVIN2 had a dramatically lower expression in lung adenocarcinoma, squamous cell lung carcinoma and large cell lung carcinoma." (PMID 37497407, 2023). "Taken together, our data suggest that lung cancer cells use Cav-2 expressed in bone marrow-derived cell types including TAMs to promote tumor growth via inhibiting the anti-tumor immune response and that Cav-2 could be a potential target for cancer immunotherapy." (PMID 31831780, 2019). "The robust anti-tumor phenotype in Cav-2 KO mice is evidenced by the results obtained using two independent syngeneic models of tumor growth in immunocompetent mice involving subcutaneous implantation with LLC and CMT 167 lung carcinoma cell lines." (PMID 31831780, 2019).
pancreatic cancer (8 papers, 2020 to 2025). "An increase in cav-2 expression has also been linked with cancer progression in aggressive forms of esophageal and pancreatic cancer." (PMID 39857963, 2025). "CAV2 had specific diagnostic significance in the area under the pancreatic cancer-specific ROC curve of 0.927, and the pancreatic cancer group with high CAV2 expression showed worse survival when compared to the low expression group." (PMID 35517414, 2022). "In our study, both CAV1 and CAV2 were identified as DEGs, but only CAV2 was a prognostic DEG associated with shorter OS in pancreatic cancer patients." (PMID 34078402, 2021). "More recently, cav-2 has been linked to the progression of lung carcinoma and the migration of pancreatic cancer cells, stimulating interest of this member of the caveolin family in pancreatic cancer." (PMID 32825713, 2020). "Few studies have reported that CAV2 exhibits different effects in breast, oesophageal and pancreatic cancers." (PMID 36830672, 2023). "We first concluded, by qRT-PCR, that the gene expression of CAV2 was significantly downregulated in pancreatic cancer cell lines overexpressing MiR-4723 compared to that in the control cells." (PMID 35517414, 2022). "We also demonstrated, for the first time, that CAV2 can regulate the MiR-4723/Wnt7A signalling axis in pancreatic cancer cells by inhibiting endocytosis and promoting EMT, thereby accomplishing its pro-cancer effects." (PMID 35517414, 2022). "The ROC curve also demonstrated that the CAV2 expression was significantly specific in the diagnosis of pancreatic cancer." (PMID 35517414, 2022). "Here, we are the first to demonstrate that CAV2 exerts a pro-carcinogenic effect on pancreatic cancer through the activation of the Wnt7A/β-catenin signalling pathway." (PMID 35517414, 2022). "Second, the results were obtained through different cytological experiments suggesting that CAV2 promotes migration, repair, invasion, cloning, and proliferation of pancreatic cancer cells." (PMID 35517414, 2022). "The cloning ability of pancreatic cancer cells overexpressing CAV2 was significantly increased compared to that in the control group." (PMID 35517414, 2022). "CAV2 was expressed at low levels in normal pancreatic tissues, and high levels in pancreatic cancer tissues, and its expression was found to increase with age in 168 pancreatic cancer patients (e.g., P < 0.05)." (PMID 35517414, 2022). "In summary, we conclude that CAV2 is an oncogenic gene in pancreatic cancer that exerts its oncogenic effect by targeting Wnt7A to activate the Wnt/β-catenin signalling pathway activity." (PMID 35517414, 2022). "Western Blotting results revealed that the protein expression of Wnt7A and β-catenin were significantly increased in pancreatic cancer cells overexpressing CAV2, and their greyscale values were statistically significant (P < 0.05)." (PMID 35517414, 2022). "Our qRT-PCR results suggest that the CAV2 expression was downregulated in pancreatic cancer with MiR-4723 upregulation." (PMID 35517414, 2022). "Our immunofluorescence assay revealed that the intranuclear expression level of β-catenin was significantly higher in CAV2 overexpressing pancreatic cancer cells when compared to that in the two control groups." (PMID 35517414, 2022). "Through qRT-PCR and Western blotting, we determined that the upregulation of CAV2 promotes the expression of Wnt7A, β-catenin gene, and proteins in pancreatic cancer cells." (PMID 35517414, 2022). "When compared to the control group, the protein and gene expression of PDGFR and EGFR was significantly lower in pancreatic cancer cells overexpressing MiR-4723, while it was significantly higher in cells overexpressing CAV2 or Wnt7A." (PMID 35517414, 2022). "In the Transwell assay, we noted that pancreatic cancer cells overexpressing CAV2 showcased a significantly higher ability to invade and metastasize when compared to the control group." (PMID 35517414, 2022).
pancreatic cancer (continued). "The Wnt7A protein and gene expression was reduced in pancreatic cancer cells overexpressing MiR-4723 and increased in cells overexpressing CAV2." (PMID 35517414, 2022). "qRT-PCR analyses revealed that the gene expression of Wnt7A and β-catenin was significantly increased in pancreatic cancer cells overexpressing CAV2 (P < 0.05)." (PMID 35517414, 2022). "These analyses yielded results showing that the correlation of expression trends between CAV2 and Wnt7A was significantly higher in pancreatic cancer and its paracancer tissues." (PMID 35517414, 2022). "In summary, we conclude that CAV2 plays a pro-carcinogenic role in pancreatic cancer and that the upregulation of CAV2 promotes the development and metastasis of pancreatic cancer." (PMID 35517414, 2022). "We found that the pancreatic cancer cells overexpressing CAV2 demonstrated a significant increase in migration, and their repairability was comparable to that of the control group." (PMID 35517414, 2022). "This experiment aimed to explore the effects of CAV2 and MiR-4723 on pancreatic cancer and deeply explore the role and mechanism of CAV2 in MiR-4723/Wnt7A." (PMID 35517414, 2022). "To investigate the mechanism by which CAV2 promotes pancreatic cancer, we identified Wnt7A as a potential target of CAV2 by using the TCGA database and bioinformatics analyses, whereby CAV2 seems to be the key regulator of Wnt7A." (PMID 35517414, 2022). "It has been demonstrated that higher expression of CAV-2 and its upstream regulator bromodomain containing 4 (BRD4) is associated with shorter overall survival of 76 pancreatic cancer patients." (PMID 34078402, 2021). "Targeting the BRD4-caveolin-2 interaction by development of BET inhibitors will be a therapeutic strategy for pancreatic cancer." (PMID 32099528, 2020). "BRD4 (high)/caveolin-2 (high) correlated with shorter overall survival of patients with pancreatic cancer." (PMID 32099528, 2020). "In addition, the CAV2 protein expression was reduced in pancreatic cancer cells overexpressing MiR-4723 and increased in cells overexpressing Wnt7A." (PMID 35517414, 2022). "The CAV2 expression also showed significance in the TNM staging of pancreatic cancer, with a higher expression in stages T3 and 4 stages when compared to that in T1 and T2; in the regional lymph node, the N stage also showed a positive statistical correlation (e.g., P < 0.05)." (PMID 35517414, 2022). "In this study, we demonstrated that CAV2 could promote invasion, migration, proliferation, and cloning of pancreatic cancer cell lines." (PMID 35517414, 2022). "Among 39 differentially expressed factors, seven up-regulated genes (CAV2, CIDEC, HILPDA, HSD17B11, NCEH1, RAB5A, and SQLE) and two down-regulation genes (BSCL2 and FITM1) were significantly associated with overall survival of pancreatic cancer patients." (PMID 34078402, 2021). "In pancreatic cancer, CAV-2 overexpression might be involved in the metastatic potential and associated with poorer prognosis with shorter overall survival and disease-free survival." (PMID 32099528, 2020). "To investigate the relationship between CAV2 and this pathway, we screened 182 pancreatic cancer-related tumour and paracancer tissue data with reference to the TCGA database and performed Zscore transformations to analyse the expression trends of CAV2 and several related genes." (PMID 35517414, 2022). "We further identified that enhanced expression of 7 genes namely CAV2, CIDEC, HILPDA, HSD17B11, NCEH1, RAB5A, and SQLE are associated with significantly shorter overall survival whereas elevated expression of BSCL2 and FITM1 correlates with longer overall survival of pancreatic cancer patients." (PMID 34078402, 2021). "We explored the cell biological functions of pancreatic cancer cells PANC-1 and BXPC-3 through lentiviral transfection to upregulate their CAV2 expression." (PMID 35517414, 2022).
pancreatic cancer (continued). "Our findings reveal the oncogenic effects of BRD4 in pancreatic cancer and elucidate a possible mechanism by which BRD4 and caveolin-2 act to enhance cell growth." (PMID 32099528, 2020). "MiR-4723 and CAV2 are mutually suppressive in the Wnt7A/β-catenin pathway, and CAV2 can regulate the MiR-4723/Wnt7A pathway by inhibiting endocytosis promoting EMT, which ultimately promotes the proliferation, invasion, and metastasis of pancreatic cancer." (PMID 35517414, 2022). "Thereby CAV2 may affect the MiR-4723/Wnt7A pathway through EMT, thus promoting pancreatic cancer." (PMID 35517414, 2022). "PANC-1 and BXPC-3 were each divided into 3 groups: pancreatic cancer cells without any treatment (blank control); pancreatic cancer cells overexpressing CAV2 via lentiviral infection (CAV2 overexpress); and pancreatic cancer cells after lentiviral infection with the blank vector (N-Control)." (PMID 35517414, 2022).
prostate carcinoma (7 papers, 2009 to 2025). A carcinoma that arises from epithelial cells of the prostate gland. "Our results confirm data from earlier studies that were obtained in breast, lung, and prostate cancer cell lines, in that high expression levels of caveolin-1, caveolin-2, annexin-1, moesin, Eph2A, and uPA were associated with in vitro sensitivity to dasatinib." (PMID 19861960, 2009). "Also, from the GAD DAS annotation, we know that CAV1 and CAV2 are associated with prostate cancer." (PMID 19919683, 2009). "Using electron microscopy, we have previously shown that in addition to Cav-1, Cav-2 is also essential for de novo assembly of caveolae in human prostate cancer cell line LNCaP." (PMID 22229094, 2011). "Earlier reports have shown that high expression of annexin-1, caveolin-1, caveolin-2, moesin, and uPA, as well as low expression of IGFBP2, was associated with the in vitro response to dasatinib in breast, lung, and prostate cancer cells." (PMID 19861960, 2009). "Importantly, Cav-2 is upregulated during prostate cancer progression." (PMID 22229094, 2011). "In contrast, CAV2 induces various epithelium-related molecules, including Vimentin, N-Cadherin, E-Cadherin, MMP13, and MYCL, which play important roles in prostate cancer cell motility." (PMID 35517414, 2022). "In prostate cancer, PTRF expression was lost, and the levels of OT became diminished, removing this regulation over caveolin alongside a consequential upregulation of cav-1 and particularly cav-2 expression." (PMID 39857963, 2025). "Since upregulation of Cav-2 in PC3 cells coincides with the absence of caveolae, this data suggests that noncaveolar Cav-2 could possibly play a positive role in prostate cancer progression." (PMID 22229094, 2011). "The detection of CAV1 and CAV2 in urine can be used to distinguish between CRPC and non-CRPC, and 12 urinary peptides have been found to be able to distinguish between prostate cancer and benign conditions." (PMID 34576294, 2021).
glioma (5 papers, 2013 to 2025). A benign or malignant brain and spinal cord tumor that arises from glial cells (astrocytes, oligodendrocytes, ependymal cells). "The statistics results mean that the lower expression of CAV2 predicts better prognosis in long-term survival of glioma patients." (PMID 32139705, 2020). "We summarized our conclusions about miR-144 regulating gliomas progression mediated by CAV2 and FGF7 as the schematic diagram exhibiting." (PMID 32139705, 2020). "The bioluminescence imaging data showed that miR-144 repressed glioma development obviously, and rescued by CAV2 or FGF7 overexpression." (PMID 32139705, 2020). "The further exploration suggested miR-144’s targets FGF7 and CAV2 modulated gliomas through Akt-ROS regulatory axis and EMT progress, respectively." (PMID 32139705, 2020). "Our data indicated miR-144 regulated glioma cells migration and invasion by inhibiting CAV2 expression." (PMID 32139705, 2020). "On the other hand, CAV2, as another target of miR-144, accelerated glioma cells migration and invasion via promoting glioma cells EMT progress." (PMID 32139705, 2020). "The consequence above had demonstrated miR-144 mediated CAV2 inhibition regulated gliomas invasion and migration by repressing EMT progress." (PMID 32139705, 2020). "The main types of Ca2+ channels described in the literature and expressed by gliomas are voltage-dependent channels (Cav1 = Type L; Cav2 = Type P/Q, R, N; Cav3 = Type T) and purinergic receptors." (PMID 31531023, 2019). "The authors showed that CAV2 expression in either neuroblastoma or hepatocellular carcinoma cells, as well as its knock-down in glioma cells, leads to reduced proliferation." (PMID 23826261, 2013). "Another interaction that has been documented in glioma is that of ELK1 with CAV2." (PMID 40862737, 2025). "Besides, the HE staining indicated that miR-144-3p overexpression inhibited the tumorigenesis, while rescue expression of CAV2 or FGF7 promoted the tumor node formation ability of patient-derived glioma cells." (PMID 32139705, 2020). "To fully understand the molecular mechanisms of miR-144 regulating glioma cells development, we identified miR-144’s targets predicted by several bioinformatic algorithms (Target Scan, PicTar, and miRDB), which suggested CAV2 and FGF7 as candidate target genes of miR-144." (PMID 32139705, 2020). "However, the mechanisms CAV2 affected EMT progress of glioma cells remained still unclear." (PMID 32139705, 2020). "The analysis data indicated lower expression of CAV2 predicted longer survival time, but FGF7 level had nothing to do with the glioma prognosis." (PMID 32139705, 2020). "We also detected the expressions of CAV2 and FGF7 in glioma tissues, which were both much higher than that in normal brain tissue." (PMID 32139705, 2020). "After identification of the overexpression efficiency of CAV2 and FGF7 by lentivirus infection, glioma cells were transfected with miR-144 as well as overexpression of its targets to validate the glioma cells proliferation and chemotherapeutics sensibility." (PMID 32139705, 2020). "The data above indicated miR-144 directly targeted CAV2 and FGF7 in glioma cells." (PMID 32139705, 2020). "The RT-PCR and western blot were also performed to detected CAV2 and FGF7 levels in glioma cells." (PMID 32139705, 2020). "It should be noticed that although CAV2 overexpression had obvious promotion on gliomas EMT, it could not retrieve the effects of miR-144 completely, which indicted some other mechanisms independent on CAV2 also modulated glioma cells EMT and migration." (PMID 32139705, 2020). "Overexpression of FGF, but not CAV2, recovered the function of miR-144 on glioma cells growth." (PMID 32139705, 2020). "Meanwhile, since CAV2 and FGF7 are downstream genes of miR-144, other miRNAs targeting CAV2 or FGF7 could be considered as the coordinative genes to suppress glioma development, which perhaps obtain better effect on CAV2-high or FGF7-high gliomas." (PMID 32139705, 2020).
lung adenocarcinoma (5 papers, 2011 to 2023). A carcinoma that arises from the lung and is characterized by the presence of malignant glandular epithelial cells. "Furthermore, the expression of Cav-2 was associated with shorter survival in stage I lung adenocarcinomas." (PMID 22229094, 2011). "Caveolin 2 (CAV2) is a member of the caveolin protein family, the down-regulation of CAV2 promote cell proliferation of HeLa epithelial cervical cancer and A549 lung adenocarcinoma cells." (PMID 35132081, 2022). "Furthermore, overexpression of Cav-2 in SH-SY5Y neuroblastoma and siRNA knockdown in HeLa epithelial cervical cancer and A549 lung adenocarcinoma cell lines promoted cell proliferation." (PMID 22229094, 2011).